HLA-V (major histocompatibility complex, class I, V (pseudogene))
Synonyms: dJ377H14.4; formerly HLA-75
Gene: Transcribed unprocessed pseudogene on chromosome 6 (29,792,234 to 29,793,136, forward strand). Ensembl gene ENSG00000181126.
Diseases named in the same sentence as HLA-V in open-access papers:
HLA-V is named in the same sentence as 1 disease in open-access papers, as found by Europe PMC text mining. Sharing a sentence is not in itself a finding about the gene and the disease. The quoted sentences say what the papers report.
mastocytosis (1 paper, 2020). A clonal myeloproliferative neoplasm characterized by the proliferation and accumulation of neoplastic mast cells in one or multiple organs or organ systems. "Four SNPs were more prevalent (in ABCA2, OTX2-AS1, HLA-V, and PDE4DIP genes) and 5 were less prevalent (in RPTN, CYP2B6, OR51Q1, FTCD, and rs9828758 near RP11 genes) in mastocytosis patients compared to a control cohort." (PMID 32752121, 2020).